LRRC32 (leucine rich repeat containing 32)
Description:
Key regulator of transforming growth factor beta (TGFB1, TGFB2 and TGFB3) that controls TGF-beta activation by maintaining it in a latent state during storage in extracellular space. Associates specifically via disulfide bonds with the Latency-associated peptide (LAP), which is the regulatory chain of TGF-beta, and regulates integrin-dependent activation of TGF-beta. Able to outcompete LTBP1 for binding to LAP regulatory chain of TGF-beta. Controls activation of TGF-beta-1 (TGFB1) on the surface of activated regulatory T-cells (Tregs). Required for epithelial fusion during palate development by regulating activation of TGF-beta-3 (TGFB3) (By similarity).
Synonyms: GARP; D11S833E; CPPRDD
Tractability: Antibody: UniProt places it where antibodies can reach, with high confidence; its Gene Ontology location is reachable by antibodies, with high confidence; UniProt predicts a signal peptide or a membrane-spanning region.
Gene: Protein-coding gene on chromosome 11 (76,657,524 to 76,670,868, reverse strand). Ensembl gene ENSG00000137507.
Subcellular location: Cell membrane; Cell surface
Subcellular location (Human Protein Atlas): Nucleoplasm
Gene Ontology:
Molecular function: protein binding; receptor ligand inhibitor activity; transforming growth factor beta binding; signaling receptor activity
Biological process: establishment of protein localization to extracellular region; transforming growth factor beta receptor signaling pathway; negative regulation of transforming growth factor beta receptor signaling pathway; secondary palate development
Cellular component: cell surface; nucleoplasm; plasma membrane
Genetic constraint (gnomAD): Loss-of-function variants: 6 observed, 16.86 expected, observed/expected ratio (o/e) 0.36, 90% interval 0.19 to 0.7. The upper end of that interval is the gene's LOEUF score, 0.7, which puts it in group 2 of 6, group 1 being the genes least tolerant of losing a copy. Missense variants: 803 observed, 886.93 expected, observed/expected ratio (o/e) 0.91, 90% interval 0.85 to 0.96. Synonymous variants: 391 observed, 423.73 expected, observed/expected ratio (o/e) 0.92, 90% interval 0.85 to 1.
Homologues: Orthologues: chimpanzee LRRC32 (99% identical), macaque LRRC32 (97% identical), dog LRRC32 (85% identical), pig LRRC32 (84% identical), guinea pig LRRC32 (84% identical), rabbit LRRC32 (83% identical), rat Lrrc32 (81% identical), mouse Lrrc32 (80% identical). Paralogues in human: NRROS (34% identical), TLR8 (26% identical), IGFALS (25% identical), TLR7 (25% identical), TLR3 (23% identical), TLR5 (21% identical), CD180 (20% identical), TLR1 (19% identical), TLR4 (19% identical), TLR10 (18% identical), TLR6 (18% identical), VASN (17% identical), and 10 more.
Diseases named in the same sentence as LRRC32 in open-access papers:
LRRC32 is named in the same sentence as 35 diseases in open-access papers, as found by Europe PMC text mining. Sharing a sentence is not in itself a finding about the gene and the disease. The quoted sentences say what the papers report.
asthma (5 papers, 2015 to 2025). "In addition, ERBB3, IL1R1, IL1RL2, IL6R, LRRC32, STAT6, and TNFRSF6B have been strongly linked to allergic diseases, such as asthma and rhinitis." (PMID 38773393, 2024). "The four loci originally discovered through GWAS on eczema (FLG, IL4/KIF3A, OVOL1 and C11orf30/LRRC32) did not reveal an effect on asthma alone." (PMID 26542096, 2015).
atopic dermatitis (4 papers, 2018 to 2025). "Additionally, the gene locus of LRRC32 was also identified as a risk locus for asthma, atopic dermatitis, and colitis." (PMID 35898500, 2022). "The tolerogenic roles of GARP might give a mechanistic explanation for atopic dermatitis manifested by patients with gene mutations in the Lrrc32 gene locus that prevents GARP surface expression." (PMID 29458436, 2018). "Indeed, a growing number of studies support a key role for GARP in immune regulation, with knockdown or inhibition of GARP reducing Treg-mediated suppression of T-effector cell activity and rare coding mutations in LRRC32 being associated with primary immunodeficiency and atopic dermatitis." (PMID 36897113, 2023). "For instance, variants at the 5q22 (TSLP/WDR36), 11q13 (LRRC32/C11orf30), and 12q13 (STAT6) loci are associated with asthma and atopic dermatitis and have been consistently associated with EoE risk 19,24." (PMID 40470207, 2025).
eczema (3 papers, 2015 to 2025). "Compared with eczema alone, the excess risk of these loci on the atopic march was not significant although a trend for FLG-null mutations and the C11orf30/LRRC32 locus was observed." (PMID 26542096, 2015).
colitis (2 papers, 2022 to 2023). Inflammation of the colon. "Investigation of this conserved region in mice found that deleting the locus increased susceptibility to colitis and decreased expression of leucine rich repeat containing 32 (Lrrc32), the gene encoding glycoprotein A repetitions predominant (GARP)." (PMID 36897113, 2023).
colon carcinoma (2 papers, 2018 to 2019). "Recent studies also demonstrate that the association and regulation of pro-TGF-β1 by LRRC32 (GARP) is responsible for Treg and platelets related immune tolerance of tumor cells in breast cancer and colon cancer." (PMID 31600200, 2019). "LRRC32 encodes GARP, and aberrant expression of GARP has been reported in human breast, lung and colon cancers." (PMID 29303984, 2018).
ovarian carcinoma (2 papers, 2021 to 2023). A malignant neoplasm originating from the surface ovarian epithelium. "Next, we identified LRRC15, LRRC32, and LRRC75A-AS1 as the three overexpressed gene signatures of the LRRC superfamily in ovarian cancer stroma." (PMID 36653841, 2023).
breast carcinoma (1 paper, 2018). "Indeed, Lrrc32 specific gene amplification was observed in human breast cancer and primary and metastatic neck lymph nodes in oral squamous cell carcinoma; moreover, in prostate cancer, Lrrc32 amplification rate increases with the decrease of hormone sensitivity." (PMID 29458436, 2018).
cleft palate (1 paper, 2022). Cleft palate is a fissure type embryopathy that affects the soft and hard palate to varying degrees. "Clinical and genetic characteristics of patients with cleft palate and retinopathy syndrome associated with LRRC32 pathogenic variants." (PMID 35656379, 2022). "In conclusion, loss of function bi-allelic pathogenic variants in LRRC32 should be considered as associated with a distinctive cleft palate-retinopathy syndrome." (PMID 35656379, 2022). "Relevant to this report, and given the genetic heterogeneity of clefting syndromes, we strongly suggest to include LRRC32 in gene panels targeted for diagnosis of patients with cleft palate." (PMID 35656379, 2022).
developmental delay (1 paper, 2022). "A single report, published in 2019, described three children with a novel autosomal recessive syndrome, characterized by cleft palate, developmental delay and proliferative retinopathy (OMIM # 619074) due to a single homozygous non-sense mutation in the LRRC32 gene." (PMID 35656379, 2022).
Immunodeficiency (1 paper, 2021). Failure of the immune system to protect the body adequately from infection, due to the absence or insufficiency of some component process or substance. "By routine screening of our patients at the immunodeficiency clinic using WES, we identified two patients bearing previously undescribed mutations in LRRC32." (PMID 34059789, 2021).
pancreatitis (1 paper, 2023). Inflammation of the pancreas. "We observed a steady increase in the expression of FOXP3, LRRC32, as well as FOSL2 and IL6 from normal through pancreatitis to PAAD." (PMID 36932385, 2023).
primary immunodeficiencies (1 paper, 2025). "al., investigating patients with primary immunodeficiencies, mutations in the GARP gene, LRRC32, was associated with severely reduced Tregs populations and reduced suppressive activity." (PMID 41333405, 2025).
viral infection (1 paper, 2021). "The overall transcriptional signature we observe is a broad one, with an induction of ISGs (not unexpected in a context of viral infection), but also of cell proliferation, and of heightened effector functions (ENTPD1, LAG3, LRRC32)." (PMID 34433692, 2021).
tumor (14 papers, 2016 to 2025). "The expression differences of LRRC15 and LRRC32 in HGSC tumour tissues and normal ovarian epithelial tissues were visualized by the GGplot2 package in R software." (PMID 36653841, 2023). "LRRC32, located in human chromosomal 11q13-14, has frequently been found to be amplified in tumor tissue, and its overexpression was found to promote Foxp3+ regulatory T cell activity, which in turn contributed to enhancing cancer progression and metastasis." (PMID 31781506, 2019). "LRRC32 showed a downwards expression trend in OC tumour tissues overall (p > 0.05)." (PMID 36653841, 2023). "Indeed, the blocking anti-GARP:TGF-β1 mAb exerted anti-tumor efficacy in platelets-specific Lrrc32 KO mice, but lost its activity in Tregs-specific Lrrc32 KO mice." (PMID 38067325, 2023). "Additionally, our ongoing work indicates that platelets may interact with tumor cells through the HMGB1/LRRC32 signaling axis, thereby influencing the tumor immune microenvironment." (PMID 40514754, 2025).
cancer (9 papers, 2016 to 2023). A tumor composed of atypical neoplastic, often pleomorphic cells that invade other tissues. "High LRRC32 expression is associated with immune evasion, increased cancer cell proliferation, and survival and represents an emerging target for cancer immunotherapy." (PMID 36982699, 2023). "Interestingly, the LRRC32 gene locus is part of a chromosomal region that was described to be altered in several human cancers." (PMID 35898500, 2022). "Interestingly, Lrrc32 gene locus is part of a chromosomic region frequently altered in human cancers." (PMID 29458436, 2018). "Pan-cancer analysis revealed that LRRC15 and LRRC32 are differentially expressed in multiple cancers." (PMID 36653841, 2023). "As suggested by Lrrc32 gene amplification, GARP protein is expressed on human cancer cells where it mediates the accumulation and subsequent activation of the circulating latent TGF-β." (PMID 29458436, 2018). "GARP (commonly known as leucine-rich repeat-containing 32) is a cell surface docking receptor for latent TGF-β, and also has been studied as a non-signal receptor on the surface of Tregs, platelets, and certain cancer cells." (PMID 34421887, 2021).
infection (2 papers, 2014 to 2017). The state of being infected such as from the introduction of a foreign agent such as serum, vaccine, antigenic substance or organism. "Inflammatory response genes, such as NOS2, IL6 and TNFRSF1B, were up-regulated while some positive regulation of inflammatory response genes, such as TLR3, STAT5 and LRRC32, were also elevated post-infection with IBDV." (PMID 28486945, 2017).
proliferative retinopathy (1 paper, 2022). "In summary, our report further expands the clinical features of cleft palate, proliferative retinopathy and developmental delay syndrome and emphasizes the association of LRRC32 pathogenic variants with this new syndrome." (PMID 35656379, 2022). "In accordance, three previously reported patients with the homozygous LRRC32 p.Arg544Ter mutation presented a distinctive syndrome, which was highlighted by the presence of cleft palate and proliferative retinopathy." (PMID 35656379, 2022).
LRRC32 also shares sentences with these, for which no sentence is quoted: allergic disease (2 papers); food allergy (2); allergic rhinitis (1); autoimmune disease (1); COVID-19 (1); Crohn disease (1); eosinophilic esophagitis (1); gastric cancer (1); glioblastoma (1); glioma (1); inflammatory bowel disease (1); lung carcinoma (1); multiple sclerosis (1); oral squamous cell carcinoma (1); prostate carcinoma (1); rhinitis (1); schizophrenia (1); ulcerative colitis (1).